TAS2R63P (taste 2 receptor member 63, pseudogene)
Synonyms: PS6; T2R63
Gene: Unprocessed pseudogene on chromosome 12 (11,048,332 to 11,049,256, reverse strand). Ensembl gene ENSG00000256019.
Diseases named in the same sentence as TAS2R63P in open-access papers:
TAS2R63P is named in the same sentence as 23 diseases in open-access papers, as found by Europe PMC text mining. Sharing a sentence is not in itself a finding about the gene and the disease.
TAS2R63P shares sentences with these, for which no sentence is quoted: tumor (8 papers); cancer (6); breast carcinoma (2); infection (2); melanoma (2); anal squamous cell carcinoma (1); cavernoma (1); cervical cancer (1); cutaneous squamous cell carcinoma (1); diabetes (1); glioblastoma (1); glioma (1); Lyme disease (1); lymph node metastasis (1); mesothelioma (1); Obesity (1); oral squamous cell carcinoma (1); renal carcinoma (1); rheumatoid arthritis (1); sarcoidosis (1); seminoma (1); Stroke (1); type 2 diabetes (1).